KRAS (KRas proto-oncogene, GTPase)
Diseases named in the same sentence as KRAS in open-access papers (continued):
Sharing a sentence is not in itself a finding about the gene and the disease.
pancreatic ductal adenocarcinoma (continued). "Here, we show that MRTX849, a covalent inhibitor targeting the KRAS-G12C mutation, leads to the reactivation of the mitogen-activated protein kinase signaling pathway in MRTX849-resistant NSCLC and pancreatic ductal adenocarcinoma." (PMID 39661665, 2024). "Previously, the coincidence of the mutated gene pair ARID1A–APOB and the mutual exclusion of the pair KRAS–APOB were observed in pancreatic ductal adenocarcinoma with significant differences." (PMID 39338204, 2024). "These two authors reported high gene fusion rates in patients with KRAS WT pancreatic ductal adenocarcinoma." (PMID 39410042, 2024). "TPX2, a critical target of KRAS, has been reported to be involved in the development of pancreatic ductal adenocarcinoma (PDAC) through the regulation of hypoxia-mediated HIF-1." (PMID 37240068, 2023). "The present study was designed to find the crucial biomarkers involved in the sotorasib (AMG 510) resistance in KRAS G12C-mutant MIA-PaCa2 cell pancreatic ductal adenocarcinoma cells." (PMID 37396909, 2023). "Mutant KRAS-induced tumorigenesis is prevalent in lung, colon, and pancreatic ductal adenocarcinomas." (PMID 37396909, 2023). "We and others have recently shown that proteins involved in the DNA damage response (DDR) are critical for KRAS-mutant pancreatic ductal adenocarcinoma (PDAC) cell growth in vitro." (PMID 36923647, 2023). "Collectively, the data highlights the promising anticancer potential of these novel PDK-targeting derivatives toward obtaining clinical candidates for combatting highly aggressive KRAS-mutant pancreatic ductal adenocarcinomas." (PMID 36835086, 2023). "This study suggests CAIX functions as a critical vulnerability in KRAS-driven pancreatic ductal adenocarcinoma." (PMID 36768903, 2023). "And it also can effectively prevent the progress of late PanINs and the development of KRAS( Kirsten Rat Sarcoma Viral Oncogene) driven pancreatic ductal adenocarcinoma promoted by diet-induced obesity." (PMID 36829129, 2023). "XP-524 suppresses KRAS activity, blocks KRAS-induced malignant transformation in vivo and improves mouse survival in transgenic mouse models of aggressive pancreatic ductal adenocarcinoma." (PMID 38135679, 2023). "For pancreatic ductal adenocarcinoma and colorectal adenocarcinoma, the predominant amino acid substitution is G12D in KRAS." (PMID 37662925, 2023). "This interested us to identify the crucial biomarkers involved in the AMG 510 resistance in the KRAS G12C-mutant MIA-PaCa2 pancreatic ductal adenocarcinoma cells." (PMID 37396909, 2023). "From the analysis, we finally conclude that the ribosomal protein RPS3 is the crucial biomarker involved in the AMG 510 resistance in the KRAS G12C-mutant MIA-PaCa2 cell pancreatic ductal adenocarcinoma cells." (PMID 37396909, 2023). "In response to hypoxia, KRAS-activated pancreatic ductal adenocarcinoma cells presented with CAIX overexpression through the stabilization of HIF1A and HIF2A, as an adaptive process to maintain pH and glycolysis." (PMID 36768903, 2023). "In lung and pancreatic ductal adenocarcinoma (LUAD and PDAC), KRAS mutation frequency reaches ~ 25 and 90% of cases respectively." (PMID 37210549, 2023).
pancreatic ductal adenocarcinoma (continued). "Collectively, the data highlights the promising anticancer potential of these novel derivatives, targeting PDK, towards obtaining clinical candidates for combatting highly aggressive KRAS-mutant pancreatic ductal adenocarcinoma." (PMID 36835086, 2023). "In this review, we describe the latest findings regarding KRAS in pancreatic ductal adenocarcinoma, along with updated preclinical and clinical data on KRAS-targeted therapy." (PMID 37894382, 2023). "In a previous work, we characterized the first clearly defined mechanism of SMYD3 oncogenic activity in KRAS-induced lung and pancreatic ductal adenocarcinoma." (PMID 35819319, 2022). "Our results show that the expression of alt-EJ components correlates with the development of precursor lesions of pancreatic ductal adenocarcinoma in the presence of oncogenic KRAS, and functions independently of the c-NHEJ pathway activity." (PMID 36077614, 2022). "Kirsten rat sarcoma viral oncogene homolog (KRAS) is one of the most frequently mutated oncogenes in human pancreatic ductal adenocarcinoma (PDAC); oncogenic KRAS mutations can be detected in approximately 92% of the PDAC genomes." (PMID 36139627, 2022). "Mutant KRAS-G12V induces pancreatic ductal adenocarcinoma in mice when expressed in embryonic acinar lineage cells whereas chronic pancreatitis is needed for KRAS-G12V to induce pancreatic tumors in adult mice." (PMID 36362357, 2022). "GOT2 is a key component of mutant KRAS (KRAS*)-mediated rewiring of glutamine metabolism in pancreatic ductal adenocarcinoma (PDA)." (PMID 35815941, 2022). "Kirsten rat sarcoma (KRAS) protein is an essential contributor to the development of pancreatic ductal adenocarcinoma (PDAC)." (PMID 36619305, 2022). "It was shown in different mouse models that in the presence of an oncogenic KRAS mutation, ADM is irreversible and leads to the development of pancreatic intraepithelial neoplasia (PanIN), which can further develop into pancreatic ductal adenocarcinoma (PDAC)." (PMID 35052641, 2022). "Regarding pancreatic ductal adenocarcinoma, autophagic flux present in these cells can be involved in tumor maintenance as KRAS-mutant cells demonstrate high basal levels of autophagy." (PMID 35883626, 2022). "Recent studies have shown that glutamine-derived aspartate is translocated to the cytoplasm via the oncogenic activation pathway of KRAS in pancreatic ductal adenocarcinoma cells." (PMID 36514121, 2022). "The G12C substitution in KRAS also happens, as has been reported, in 3% of all colorectal cancers and 2% of all pancreatic ductal adenocarcinomas, while, based on TCGA database, the incidence of G12C substitution in colon cancers reaches 11%." (PMID 35053550, 2022). "KRAS-driven metabolic reprogramming is a known peculiarity features of pancreatic ductal adenocarcinoma (PDAC) cells." (PMID 36123703, 2022). "In contrast, an analysis of cBioPortal data revealed that KIF4A was upregulated in KRAS-mutant pancreatic ductal adenocarcinoma patient tissues." (PMID 36499051, 2022). "HnRNPA2B1 interacted and regulated oncogenic KRAS signaling in pancreatic ductal adenocarcinoma cells." (PMID 35875075, 2022). "Pancreatic ductal adenocarcinoma (PDAC) is a highly lethal disease and oncogenic KRAS mutations are prevalent in PDAC patients." (PMID 35681705, 2022). "MALAT1, as a molecular sponge of miR-217, an inhibitor of KRAS, promotes KRAS signaling in pancreatic ductal adenocarcinoma (PDAC)." (PMID 34489556, 2022).
pancreatic ductal adenocarcinoma (continued). "Tubular adenocarcinoma is morphologically similar to conventional pancreatic ductal adenocarcinoma (PDAC) and is associated with pancreaticobiliary/gastric-type IPMN, and KRAS mutation." (PMID 36611356, 2022). "In 2019, McDonald and colleagues evaluated the potential of SLC-0111 to improve therapeutic outcomes in pancreatic ductal adenocarcinomas expressing an activated form of Ki-ras2 Kirsten rat sarcoma (KRAS) oncogene." (PMID 34948200, 2021). "Pancreatic ductal adenocarcinoma (PDAC), one of the most lethal cancers, is driven by oncogenic KRAS mutations." (PMID 33676427, 2021). "Pancreatic ductal adenocarcinoma (PDAC), one of the most aggressive solid malignancies, is characterized by the presence of oncogenic KRAS mutations, poor response to current therapies, prone to metastasis, and a low 5-year overall survival rate." (PMID 33718171, 2021). "Based on next-generation sequencing (NGS), we firstly presented a case about a KRAS wild-type pancreatic ductal adenocarcinoma patient harboring a concurrent targetable rare somatic novel KANK1-ALK, UPP2-NTRK3 fusion, and pathogenetic germline BRCA mutation." (PMID 34671564, 2021). "In line with the Hsp90 connection to K-Ras, a synergistic activity of Hsp90 inhibitors with MAPK-pathway inhibitors in KRAS mutant pancreatic ductal adenocarcinoma was reported." (PMID 33672199, 2021). "In another example, in genetically engineered mouse models of KRAS-driven pancreatic ductal adenocarcinomas, the reemergence of tumors after withdrawal of oncogenic KRAS is driven by amplification of YAP." (PMID 34265306, 2021). "Instead, its expression is regulated by transforming growth factor (TGF)-β in A549 cancer cells and by epidermal growth factor receptor/KRAS-ERK signaling pathways in pancreatic ductal adenocarcinoma (PDAC)." (PMID 33898417, 2021). "Most mutations affect the KRAS isoform (~86%), which is predominant in NSCLC, CRC, pancreatic ductal adenocarcinoma (PDAC), LGSOC, and EC." (PMID 34064352, 2021). "As such, even with effective complete KRAS inhibition, some KRAS-mutant pancreatic ductal adenocarcinoma cells survive and thrive." (PMID 34064232, 2021). "Pancreatic ductal adenocarcinoma (PDAC) is one of the most lethal malignancies and KRAS (Kirsten rat sarcoma 2 viral oncogene homolog) mutations have been considered a critical driver of PDAC initiation and progression." (PMID 33668583, 2021). "UCA1 functions as a competing endogenous RNA (ceRNA) to increase the expression of KRAS via sponging miR-590–3p in pancreatic ductal adenocarcinoma; KRAS, in turn, promotes the UCA1 expression." (PMID 34134622, 2021). "We apply genetic screens to delineate modulators of KRAS mutant pancreatic ductal adenocarcinoma (PDAC) sensitivity to ERK inhibitor treatment, and we identify components of the ATR-CHK1 DNA damage repair (DDR) pathway." (PMID 34852220, 2021). "Here, we use a mouse model of pancreatic ductal adenocarcinoma to inactivate KRAS by CRISPR-mediated genome editing." (PMID 33674596, 2021). "Among mutationally activated RAS genes (HRAS, KRAS, and NRAS), KRAS is the predominant isoform and is exclusively mutated in pancreatic ductal adenocarcinoma (PDAC)." (PMID 34829828, 2021). "The background histogram shows a distribution of an in-house drug combination dataset, consisting of 60 drug combinations tested against 16 KRAS-mutants pancreatic ductal adenocarcinoma cell lines." (PMID 33262326, 2020). "Knockdown of HNRNPA2B1 using small hairpin RNAs impaired tumor viability and proliferation via inactivating c-Akt signaling pathway in KRAS phosphorylation-dependent pancreatic ductal adenocarcinoma cells." (PMID 32710725, 2020).
pancreatic ductal adenocarcinoma (continued). "Previous studies revealed that oncogenic KRAS contributes to the production of GM-CSF and to the expansion of MDSCs in a mouse model of pancreatic ductal adenocarcinoma." (PMID 33603745, 2020). "Pancreatic ductal adenocarcinoma (PDAC) is a deadly disease, whose main molecular trait is the MAPK pathway activation due to KRAS mutation, which is present in 90% of cases." (PMID 33115526, 2020). "Many risk factors have been shown to increase the incidence of these neoplasms including diabetes mellitus, as in our case, chronic pancreatitis, family history of pancreatic ductal adenocarcinoma, and mutations in GNAS and KRAS genes." (PMID 32900376, 2020). "In the context of KRAS-driven pancreatic ductal adenocarcinoma with mutant KRAS, glutamine is pivotal both to induce cancer-promoting ROS production and to fuel antioxidant pathways, resulting in an increased homoeostatic ROS set point." (PMID 31819197, 2020). "A study demonstrated that one of the mechanisms of KRAS in inducing pancreatic ductal adenocarcinoma is by up-regulating GOT1 and inhibiting glutamate dehydrogenase 1 (GLUD1), thus reprogramming glutamine metabolism." (PMID 32266153, 2020). "Proliferation of pancreatic ductal adenocarcinoma cells were inhibited in vitro and in vivo with deltarasin, which inhibits the PDEδ-KRAS interaction." (PMID 29382159, 2018). "Cxcr2 antagonists not only to reduce metastasis, tumor growth and improve response to chemotherapy in the xenograft model, but suppress inflammation-driven intestinal adenocarcinomas and improve survival in a KRas-driven pancreatic ductal adenocarcinoma model." (PMID 29487713, 2018). "STAT3 is required for pancreatic ductal adenocarcinoma progression in tumors harboring activated KRAS." (PMID 29382159, 2018). "Pancreatic ductal adenocarcinoma (PDAC) cells display varying degrees of reliance on oncogenic KRAS." (PMID 30470748, 2018). "Although water-insoluble, in mice Mycro3 was amenable to daily administration by oral gavage as an emulsion for treatment of oncogenic KRAS (KRAS*)-induced pancreatic ductal adenocarcinoma (PDA), which is dependent on Myc activity." (PMID 30597997, 2018). "The KRAS oncogene, present in over 90% of pancreatic ductal adenocarcinomas, is most frequently the result of one of three gain-of-function substitution mutations of codon 12 glycine." (PMID 29851957, 2018). "Previous studies in mouse models have demonstrated that KRAS is capable of initiating pancreatic ductal adenocarcinoma and continuous signalling is required for its progression and maintenance at the primary and metastatic sites." (PMID 28445400, 2017). "KRAS is the most frequently mutated gene in pancreatic ductal adenocarcinoma (PDAC), but the mechanisms underlying the transcriptional response to oncogenic KRAS are still not fully understood." (PMID 28141826, 2017). "In pancreatic ductal adenocarcinoma, miR-217 inhibits tumor cell growth by targeting KRAS and SIRT1." (PMID 28437471, 2017). "Pancreatic ductal adenocarcinoma (PDAC) is a KRAS-driven cancer with a high incidence of metastasis and an overall poor prognosis." (PMID 28915575, 2017). "We focused on pancreatic ductal adenocarcinoma (PAAD), as incidence of KRAS-activating mutations in this tumour type is above 80%." (PMID 28581519, 2017). "MiR-217 was first illustrated to function as a potential tumor suppressor by targeting KRAS in pancreatic ductal adenocarcinoma." (PMID 28437471, 2017).
pancreatic ductal adenocarcinoma (continued). "They showed that miR-206 suppressed the pancreatic ductal adenocarcinoma cell cycle progression, migration, invasion and proliferation by targeting KRAS and annexin a2 (ANXA2)." (PMID 27906963, 2016). "A recent study identified YAP1 as essential KRAS effector in the development of pancreatic ductal adenocarcinoma." (PMID 26716514, 2016). "YAP also functions as a critical transcriptional switch downstream of the oncogenic KRAS-MAPK pathway for neoplastic progression to pancreatic ductal adenocarcinoma." (PMID 26262877, 2015). "The results indicate that the expression of the RBM5 protein is reversely correlated with the expression of the KRAS protein in pancreatic ductal adenocarcinomas (R=−0.892, P<0.01)." (PMID 23425895, 2013). "Collectively, expression of RBM5 and KRAS in pancreatic ductal adenocarcinomas is significantly decreased and increased, respectively, compared to non-tumor tissues." (PMID 23425895, 2013). "By Spearman’s rank test, we analyzed the correlation between protein expression of RBM5 and KRAS in 45 pancreatic ductal adenocarcinomas." (PMID 23425895, 2013). "However, if ADM persists under chronic inflammation or oncogenic KRAS activation, it can facilitate the initiation of pancreatic ductal adenocarcinoma." (PMID 42237897, 2026). "Despite the high prevalence of KRAS alterations in pancreatic ductal adenocarcinoma (PDAC), the clinical impact of common KRAS mutations with different cytotoxic regimens is unknown." (PMID 39777438, 2025). "KRAS-dependent acinar-to-ductal metaplasia (ADM) is a fundamental step in the development of pancreatic ductal adenocarcinoma (PDAC), but the involvement of cell death pathways remains unclear." (PMID 39971907, 2025). "Pancreatic ductal adenocarcinoma (PDAC) presents yet another distinct pattern, with KRAS G12C mutations detected in only 2–3% of cases, despite the high (>90%) overall frequency of KRAS mutations in this tumor type." (PMID 40940900, 2025). "In the treatment of pancreatic ductal adenocarcinoma (PDAC), although targets such as KRAS and BRCA mutations have received considerable attention, their clinical application is often constrained by mutation frequencies or limitations to specific patient subgroups." (PMID 40290442, 2025). "Specifically, higher ferritin levels are correlated with poorer pancreatic ductal adenocarcinoma (PDAC) prognosis; however, the underlying mechanism and metabolic programming of ferritin involved in KRAS-mutant PDAC progression remain unclear." (PMID 39294443, 2024). "To determine whether KRAS-dependent tumor cells are co-dependent on STAT3, we used two wellestablished models of KRAS mutant cancer: mouse embryonic fibroblasts and pancreatic ductal adenocarcinoma (PDAC) cells expressing endogenous KRASG12D." (PMID 38573819, 2024). "KRAS oncogenic point mutations, which constitutively activate the RAS signaling pathway, affect the regulation of multiple cellular biological processes in pancreatic ductal adenocarcinoma, including cell proliferation, migration, metabolism and autophagy." (PMID 38821916, 2024). "In addition to EV-DNA detection for the diagnosis of pancreas-associated pathologies, the clinical utility of EV-DNA and cfDNA KRAS MAFs in patients with localized and metastatic pancreatic ductal adenocarcinoma was determined, and the results were compared." (PMID 39402599, 2024).